CCL3 (C-C motif chemokine ligand 3)
Diseases named in the same sentence as CCL3 in open-access papers (continued):
Sharing a sentence is not in itself a finding about the gene and the disease.
schistosomiasis (6 papers, 2009 to 2022). An infectious disease caused by parasitic trematodes of the genus Schistosoma that colonize human blood vessels and release eggs that can cause granulomatous reactions leading to acute (swimmer's itch or acute schistosomiasis syndrome) or chronic disease. "Some studies have identified MIP-1α/CCL3 as a marker of disease severity in S. mansoni infected individuals and experimental studies in mice suggest that MIP-1α/CCL3 may be a causative factor in the development of severe schistosomiasis." (PMID 19852800, 2009). "Moreover, CCL3 has been associated with fibrosis and hepatosplenic forms of human schistosomiasis." (PMID 33777015, 2021). "HSCs can also be activated during the chronic stage of schistosomiasis, and in turn, they can produce chemokines like CCL2, CCL3, and CXCL-10 following liver injury." (PMID 35839247, 2022). "On the other hand, especially CCL3 and CCL5 were shown to be elevated in schistosomiasis patients with severe disease." (PMID 30619332, 2018). "Outcome measures consisted of HIV-1 and schistosomiasis status and levels of MIP-1α/CCL3 in plasma at baseline and three months post treatment." (PMID 19852800, 2009). "This is in agreement with findings by other investigators on S. mansoni infection who demonstrated a positive correlation between elevated plasma concentrations of MIP-1α/CCL3, egg counts and presentation of severe schistosomiasis in humans." (PMID 19852800, 2009). "We hypothesized that schistosomiasis would induce systemic inflammation indicated by the levels of circulating soluble MIP-1α/CCL3, a proinflammatory chemokine, and observed the effects of schistosomiasis treatment with praziquantel." (PMID 19852800, 2009).
Sjögren’s syndrome (6 papers, 2023 to 2025). "We have previously shown significantly upregulated levels of CXCL10 and CCL3 chemokines in saliva from Sjögren’s syndrome patients." (PMID 39436967, 2025). "Finally, increased expression of CCR5 and its ligand CCL3 was demonstrated in the tear film and ocular surface of patients with dry eye syndrome, especially in those with Sjogren’s syndrome." (PMID 39104520, 2024). "In this study, we found an upregulation of CXCL10 and CCL3 in Primary Sjögren’s syndrome (pSS) patients compared with non-SS sicca controls." (PMID 39436967, 2025).
acute myeloid leukemia (5 papers, 2014 to 2025). Acute myeloid leukemia (AML) is a group of neoplasms arising from precursor cells committed to the myeloid cell-line differentiation. "CCL3 causes the recruitment of Treg to the leukemic hematopoietic microenvironment, which promotes the development of acute myeloid leukemia." (PMID 33076281, 2020). "In addition, the production of CCL3 by acute myeloid leukemia cells causes severe anemia by inhibiting erythropoiesis." (PMID 33076281, 2020). "The autocrine production of CCL3 together with CCR5 expression would facilitate the retention of the acute myeloid leukemia blasts in the skin." (PMID 24591756, 2014). "Also in acute myeloid leukemia cells chronic hypoxia increases CCL3/MIP-1α release." (PMID 32781743, 2020). "CCR5/CCL3 and CXCR4/CXCL12 interactions facilitate the retention of acute myeloid leukemia cells in the skin, and CXCR7/CXCL12 interactions subsequently prolong their survival." (PMID 24591756, 2014). "A significant secretion of CCL3, CCL2, CCL4, CXCL1, and CXCL8 exists in acute myeloid leukemia (AML) cells." (PMID 40148973, 2025).
allergic disease (5 papers, 2018 to 2022). An immune response that occurs following re-exposure to an innocuous antigen, and that requires the presence of existing antibodies against that antigen. "TNF and CCL3 are famous cytokines and broadly take part in regulating many immune cells and developing inflammatory and allergic diseases." (PMID 36531995, 2022). "CCL3 also correlated with some aspects of respiratory allergies, such as polysensitization, seasonal allergies, and nasal mucosal hypertrophy." (PMID 32461855, 2020). "Also, high levels of CCL3 messenger RNA were induced in mouse macrophage RAW 264.7 cells by birch and oak dusts, which have been associated with the development of allergic diseases." (PMID 32461855, 2020). "did provide a proof that acteoside could alleviate inflammatory response by down-regulating the expression of CCL1, CCL2, CCL3 and CCL4 in allergy." (PMID 29708439, 2018).
Chagas disease (5 papers, 2010 to 2025). A parasitic infection caused by Trypanosoma cruzi. "CCL3, a member of the CC-chemokine family, has been associated with macrophage recruitment to heart tissue and parasite control in the acute infection of mouse with Trypanosoma cruzi, the causative agent of Chagas disease." (PMID 32194558, 2020). "Particularly, for the first time, CCL3 is proposed to contribute to heart dysfunction and QTc prolongation, biomarkers of prognosis for CCC severity and mortality risk in Chagas disease." (PMID 32194558, 2020). "A recent study found higher levels of interferon-gamma, tumor necrosis factor-alpha, interleukin-10 and CCL3 in the myocardium of hamsters exhibiting acute symptoms of Chagas disease, when compared to asymptomatic animals." (PMID 20559542, 2010). "Moreover, given the role of CCL3 in autoimmune myocarditis and Chagas disease, CaMKII might also be a promising drug target in these disease entities." (PMID 25193973, 2014). "Here, we approached the participation of CCL3 in chronic chagasic cardiomyopathy (CCC), the main clinical form of Chagas disease." (PMID 32194558, 2020).
chondrosarcoma (5 papers, 2013 to 2021). A malignant cartilaginous matrix-producing mesenchymal neoplasm arising from the bone and soft tissue. "In this study, we observed that CCL3 increases the migration of human chondrosarcoma cells and upregulates the expression of MMP-2." (PMID 24047437, 2013). "Taken together, these data suggest that activation of the CCR5 receptor, AMPK, and p38 are required for CCL3-induced NF-κB activation in human chondrosarcoma cells." (PMID 24047437, 2013). "Taken together, our results indicate that CCL3 enhances the migratory ability of human chondrosarcoma cells by increasing MMP-2 expression via the CCR5, AMPK, p38, and NF-κB pathways." (PMID 24047437, 2013). "To determine the identity of the catalytic subunit of AMPK that mediates CCL3 signaling in human chondrosarcomas, we performed a migration assay by using cells transfected with siRNA specific for either AMPKα1 or AMPKα2." (PMID 24047437, 2013). "Pre-treatment of chondrosarcoma cells with CCR5 mAb or inhibitor blocked CCL3-induced cell migration and reduced MMP-2 expression." (PMID 24047437, 2013). "Immunohistochemical analyses revealed that the expression of CCL3 in chondrosarcoma patients was higher than that in normal cartilages." (PMID 24047437, 2013). "We attempted to determine the identity of the catalytic subunit of AMPKα1 or AMPKα2, which mediates CCL3 signaling in human chondrosarcoma cells." (PMID 24047437, 2013). "Direct administration of exogenous CCL3 promoted cell migration, invasion, and wound healing activity in chondrosarcoma cells." (PMID 24047437, 2013). "Since it has also been reported that AMPK interacts with p38 to regulate cell motility in human chondrosarcoma, we examined the potential role of p38 in the signaling pathway of CCL3-induced migration activity." (PMID 24047437, 2013). "Pre-treatment of chondrosarcoma cells for 30 min with SB203580 or transfection with the p38 mutant for 24 h markedly attenuated the CCL3-induced migration activity and MMP-2 expression." (PMID 24047437, 2013). "We therefore directly examined migration in human chondrosarcoma cell lines in response to CCL3 by using Transwell and wound-healing migration assays." (PMID 24047437, 2013). "In this study, immunohistochemical staining revealed that high levels of CCL3 expression strongly correlated with CCR5 expression in human chondrosarcoma patients." (PMID 24047437, 2013). "Notably, chemokine (C-C motif) ligand 3 (CCL3)-facilitated increases in MMP-2 synthesis in chondrosarcoma cells encourage their migratory abilities, while inhibition of MMP-2 expression abolishes this effect of CCL3." (PMID 34445345, 2021). "In our previous study, we demonstrated that CCL3 promotes metastasis of human chondrosarcoma cells." (PMID 26713602, 2016). "In this study, we hypothesized and investigated the paradigm that CCL3 may direct the metastasis of chondrosarcomas." (PMID 24047437, 2013). "In addition, we observed that treatment of chondrosarcoma cells with CCL3 induced increased p38 phosphorylation." (PMID 24047437, 2013). "In addition, treatment of the chondrosarcoma with CCL3 resulted in time-dependent phosphorylation of p38." (PMID 24047437, 2013). "We therefore hypothesized that MMPs may be involved in CCL3-induced chondrosarcoma migration." (PMID 24047437, 2013). "We also used western blotting to confirm the results from immunohistochemistry that the expression of CCL3 and MMP-2 in chondrosarcoma was also significantly higher than that in chondrocytes." (PMID 24047437, 2013). "However, the effect of CCL3 on human chondrosarcoma metastasis is still unknown." (PMID 24047437, 2013). "The data therefore suggest that AMPKα1 and AMPKα2 are involved in CCL3-mediated migration activity and MMP-2 expression in chondrosarcoma." (PMID 24047437, 2013). "The expression of CCL3, CCR5, and MMP-2 in chondrosarcoma specimens was significantly higher than that in normal cartilage." (PMID 24047437, 2013).
chondrosarcoma (continued). "Our data suggest that CCL3 increases MMP-2 expression and subsequently promotes cell migration in human chondrosarcoma cells." (PMID 24047437, 2013). "In this study, we found that while CCL3 induced MMP-2 expression and secretion in human chondrosarcoma cells, treatment of cells with the MMP-2 inhibitor reduced CCL3-induced cell migration." (PMID 24047437, 2013). "Here, we found that CCL3 induced MMP-2 expression and subsequently promoted migration in human chondrosarcoma through activation of the CCR5 receptor, AMPK, p38, and NF-κB signaling pathways." (PMID 24047437, 2013). "Taken together, these results indicate that CCL3, CCR5, and MMP-2 expression are correlated in human chondrosarcoma specimens." (PMID 24047437, 2013). "Here, we found that CCL3 increased cellular migration and expression of matrix metalloproteinase (MMP)-2 in human chondrosarcoma cells." (PMID 24047437, 2013). "Moreover, CCL3 enhances cell migration and metastasis by up-regulating matrix metalloproteinase-2 (MMP)-2 expression in chondrosarcoma cells." (PMID 26713602, 2016). "Despite this, the role of AMPK activation in CCL3-mediated cancer migration has not been investigated in chondrosarcomas." (PMID 24047437, 2013). "Therefore, blocking CCR5 reduced CCL3-mediated cell migration and MMP-2 expression in human chondrosarcoma cells." (PMID 24047437, 2013). "Furthermore, the expression levels of CCL3, CCR5, and MMP-2 were correlated in human chondrosarcoma specimens." (PMID 24047437, 2013). "However, the expression of CCL3, CCR5 and MMP-2 in chondrosarcoma is still unknown." (PMID 24047437, 2013).
cognitive decline (5 papers, 2021 to 2025). "By contrast, in subacute and chronic phases, persistent autophagic stress, impaired flux, and upregulation of SASP factors and ceRNA networks (e.g., MALAT1–miR-26b, CCL3) contribute to sustained neuroinflammation and cognitive decline." (PMID 41007413, 2025). "MIP1A/CCL3 and eotaxin/CCL11 are linked to AD, MCP1/CCL2 levels correlate with neuroinflammation, brain atrophy, and cognitive decline in AD, and MCP3/CCL7 is part of a diagnostic panel for AD." (PMID 39574895, 2024).
coronary artery disease (5 papers, 2013 to 2024). "Other proteins associated with incident HF in our research have been linked to coronary heart disease (ANG, C1QTNF1 and CCL3) and thromboembolism (SERPINA5) with the potential to induce myocardial damage." (PMID 35945262, 2022). "It was shown that human miR-103-3p was suppressed in EAT of coronary artery disease patients is one of the possible mechanisms targeting a chemokine CCL3 in EAT." (PMID 29881354, 2018). "CCL3, CCL18, CXCL12/SDF-1, CXCL16, IGF1 and IL10 have been linked to pro-angiogenesis and/or coronary artery diseases." (PMID 23496821, 2013).
Cryptococcus neoformans infection (5 papers, 2009 to 2024). "Paradoxically, CCL3 gene-deletion results in augmented neutrophil and eosinophil recruitment in response to Cryptococcus neoformans infection." (PMID 19298652, 2009). "Indeed, CCL3 is crucial for control of Cryptococcus neoformans infection in lung and brain, hepatitis virus infection in the central nervous system and Listeria monocytogenesis disseminated infection." (PMID 32194558, 2020). "Among the inflammatory cytokines produced from these pathways include CCL3, CXCL8, IL-12, and IL-23 which each contribute to the control of a cryptococcal infection through recruitment of other immune cells or enhancing a Th1 or Th17 adaptive immune response." (PMID 36466930, 2022).
delirium (5 papers, 2015 to 2025). A disorder characterized by confusion; inattentiveness; disorientation; illusions; hallucinations; agitation; and in some instances autonomic nervous system overactivity. "IL-6, IL-8, IL-10, IL-18, TNF-α, and chemokines (CCL2, CCL3, CXCL1, and CXCL10) have also been reported to be elevated in ICU delirium patients and are associated with delirium severity." (PMID 39308447, 2024). "However, there are no data whether delirium is associated with M1 macrophage, Th1, Th2, Th17, Treg or CIRS cytokine profiles, and whether a neurotoxic cytokine profile including M1, Th1, Th17 and neurotoxic chemokines, such as CCL11, CCL2, CCL3, CCL5, and CXCL10) is associated with delirium." (PMID 35641947, 2022).
diabetic retinopathy (5 papers, 2008 to 2022). "CCL3 has also been associated with diabetic retinopathy and the onset of early diabetic retinal damage." (PMID 35266958, 2022).
eosinophilia (5 papers, 2016 to 2023). "Airway eosinophilia and the levels of IL-4, IL-5, and IL-13 were attenuated by the anti-CCL3 antibody." (PMID 27829417, 2016). "In the study population, S. mansoni-infected individuals showed a higher rate of eosinophilia, higher serum concentrations of CCL3 and CCL17, and a higher frequency of IL-17 responders in comparison with all the other groups of non-Schistosoma-infected individuals." (PMID 33777015, 2021). "When assessed in combination with eosinophilia (i.e. > 400 cells/μl) and absolute WBC count, a panel comprising eosinophilia, IL-9 and CCL3 was highlighted as having 87.6% AUC (85.3% SP–87.5% SE), as soon as two out of the three variables are above (or below) their respective cut-offs." (PMID 33059754, 2020).
fungal infection (5 papers, 2013 to 2024). "In addition, genetic studies revealed single nucleotide polymorphisms (SNPs) in CCL3 and CCL4, which are significantly correlated to fungal infections." (PMID 30563459, 2018). "Among these genes those related to host defense against fungal infection were upregulated between 2 and 6 hours of exposure to the fungus, such as IL-1β, IL-8, CXCL2, CCL4, CCL3, and CCL20, coinciding with an increase in phagocytosis." (PMID 23984400, 2013). "Compared to TNF-α and IL-10, CCL3/MIP-1⍺ plays an important role in recruiting various cells such as monocytes, macrophages, lymphocytes, and eosinophils via the CCR1 or CCR5 receptor, thereby strengthening the immune response against a fungal infection." (PMID 38967888, 2024).
Hypertension (5 papers, 2012 to 2024). The presence of chronic increased pressure in the systemic arterial system. "Hypertension was associated with increased levels of both pro-inflammatory (CCL3) and anti-inflammatory (IL-10) cytokines." (PMID 36769452, 2023). "In our OSA patients with concomitant arterial hypertension, there were increased concentrations of CCL3 and IL-10." (PMID 36769452, 2023). "The comparison of OSA patients without any other diseases with OSA patients with only hypertension also demonstrated increased concentrations of CCL3 and, additionally, increased concentrations of CX3CL1/Fractalkine and IL-7." (PMID 36769452, 2023).
mastitis (5 papers, 2016 to 2025). Inflammation of breast tissue during lactation or postpartum due to an obstructed duct or infection. "Besides, CCL3, CCL4, CCL5 and CCL20 have also been reported as differentially expressed in response to mastitis by other investigators." (PMID 36336691, 2022).
nephritis (5 papers, 2010 to 2024). Inflammation of renal tissue. "Together, these data indicate that CCL3 contributes, at least in part, to the development of nephritis, probably by increasing the recruitment of macrophages." (PMID 25132730, 2014). "Our finding that CCL3 inhibition enhances pathology is similar to the finding that in a model of nephritis CCR1−/− (the main receptor for CCL3) mice have enhanced pathology associated with increased TNF levels." (PMID 20195359, 2010). "Consistently, our in vivo data showed that the expression levels of CCL2, CCL3, CCL4, CCL5, CCL19, and CXCL10 increased in the kidney of MRL.Faslpr mice during the development of nephritis." (PMID 37567910, 2023).
non-alcoholic fatty liver disease (5 papers, 2021 to 2025). "That study examined the role of the chemokine CCL3 in nonalcoholic fatty liver disease, finding that it colocalizes with M1-like pro-inflammatory macrophages in the liver, indicating its involvement in macrophage infiltration and polarization." (PMID 39941858, 2025). "In the obese state, the expression of CCL3 is elevated in both circulating blood and adipose tissues, playing a significant role in the development of Non-alcoholic fatty liver disease (NAFLD), which is induced by diets high in cholesterol and fat." (PMID 39334887, 2024). "Moreover, a recent systematic review and meta-analysis suggested that the chemokines, CCL3, CCL4, CCL5, CCL20, CXCL8 and CXCL11, are implicated in the pathogenesis of non-alcoholic fatty liver disease, post-traumatic stress disorder, and also different types of cancers." (PMID 35242125, 2021). "Moreover, a recent systematic review and meta-analysis suggested that chemokines, CCL3, CCL4, CCL5, CCL20, CXCL8 and CXCL11, are implicated in the pathogenesis of non-alcoholic fatty liver disease, post-traumatic stress disorder, and also different types of cancers." (PMID 34054797, 2021).
oral cancer (5 papers, 2015 to 2025). "CCR 5 has two ligands, CCL3 and CCL5, and recently was reported that the axis composed by CCR5 and associated chemokines has pro-tumorigenic effect, playing an important role in oral cancer progression." (PMID 31011147, 2019). "Consistently, oral carcinoma cell lines also express CCL3 and CCR5." (PMID 28881626, 2017). "This is the first study to provide mechanistic data linking CCL3/CCR5 to oral cancer." (PMID 28881626, 2017). "Therefore, the use of specific drugs to inhibit CCL3/CCR5 activity could represent potential strategies for oral cancer." (PMID 28881626, 2017). "Several chemokine ligands (chemokine (C-C motif) ligand 3 (CCL3), chemokine (C-X-C motif) ligand 2 (CXCL2), and chemokine (C-X-C motif) ligand 3 (CXCL3)) also demonstrated >25-fold overexpression in 4-NQO-induced oral cancers." (PMID 25635769, 2015). "CCL3 is also overexpressed in human oral cancers, providing additional evidence of the molecular relevance of the 4-NQO rat oral cancer model to human oral malignancy." (PMID 25635769, 2015). "The chemokine ligands, CCL3, CXCL2, and CXCL3, were each overexpressed by > 25-fold in NQO-induced oral cancers." (PMID 25635769, 2015). "Both CCL5/CCR5 axis and CCL3/CCR5 axis may be involved in the migration and proliferation of oral cancer cells." (PMID 34124265, 2021).